SFTPB (surfactant protein B)
Diseases named in the same sentence as SFTPB in open-access papers (continued):
Sharing a sentence is not in itself a finding about the gene and the disease.
acute respiratory distress syndrome (10 papers, 2010 to 2024). Progressive and life-threatening pulmonary distress in the absence of an underlying pulmonary condition, usually following major trauma or surgery. "Patients with Adult Respiratory Distress Syndrome (ARDS) and Acute Lung Injury (ALI) have low concentrations of disaturated-phosphatidylcholine and surfactant protein-B in bronchoalveolar lavage fluid." (PMID 21429235, 2011).
pulmonary fibrosis (10 papers, 2006 to 2024). Chronic progressive interstitial lung disorder characterized by the replacement of the lung tissue by connective tissue, leading to progressive dyspnea, respiratory failure, or right heart failure. "Thus, our study indicated the associations of SFTPB with the pathogenesis of pulmonary fibrosis." (PMID 38855869, 2024). "While surfactant protein-B (SP-B), produced by AT2 cells, is known to inhibit hydrolysis of surfactant phospholipids by sPLA2, AT2 hyperplasia is the key pathological feature of pulmonary fibrosis." (PMID 37048117, 2023). "To evaluate the longitudinal expression of SFTPB in lung, serum, serum EVs, and bronchoalveolar lavage fluid (BALF) during the development of fibrosis, we utilized a mouse model of bleomycin-induced pulmonary fibrosis." (PMID 38855869, 2024).
COVID-19 (9 papers, 2020 to 2025). A disease caused by infection with severe acute respiratory syndrome coronavirus 2. "The expression of SFTPB decreased significantly by 1.44-fold in the mild group compared to the asymptomatic COVID-19-positive patient group (p = 0.0482) and by 1.73-fold in the severe group compared to the mild group (p = 0.0120)." (PMID 40647689, 2025). "Finally, six plasma proteins were found to mediate the causal effect between LTL and COVID-19 outcomes, such as BDNF, QPCT, FAS, MPO, SFTPB, and APOF." (PMID 38882679, 2024). "Furthermore, six proteins partially mediated the causality of LTL on COVID-19 outcomes, including BNDF, QPCT, FAS, MPO, SFTPB, and APOF." (PMID 38882679, 2024). "A prospective observational cohort study revealed that autoimmunity in severe COVID-19 patients is mediated through binding of immunoglobulin A (IgA) antibodies to human surfactant protein B (SP-B) and surfactant protein C (SP-C) leading to reduced levels of pulmonary surfactant." (PMID 34267664, 2021). "In this study, we compared the expression of SFTPA1, SFTPA2, SFTPB, SFTPC, and SFTPD in blood among asymptomatic, mild, and severe COVID-19 patients to identify patterns related to disease severity." (PMID 40647689, 2025). "This study aimed to elucidate the effect of COVID-19 on the lung’s surface tension regulatory system by examining the expression of surfactant protein genes (SFTPA1, SFTPA2, SFTPB, SFTPC, and SFTPD) across different disease severity groups." (PMID 40647689, 2025). "But in COVID-19-affected lung, TTF1 and SFTPC genes were found to be downregulated, whereas SFTPB was upregulated." (PMID 33173052, 2020).
heart failure (8 papers, 2012 to 2025). Inability of the heart to pump blood at an adequate rate to meet tissue metabolic requirements. "A model based on 12 HDL proteins that included SFTPB was a significant predictor of death in patients with heart failure." (PMID 35300983, 2022). "Increased circulating plasma levels of surfactant protein B have been reported in heart failure patients with a good correlation with heart failure severity." (PMID 23365739, 2012).
cystic fibrosis (7 papers, 2008 to 2024). Autosomal recessive disorder caused by pathogenic variants in the CFTR gene (cystic fibrosis transmembrane conductance regulator), which encodes a chloride and bicarbonate channel expressed in epithelial cells, and follow the diagnosis criteria. "The rSIV.F/HN vector is being developed for conducting airway disorders such as cystic fibrosis, and also a range of parenchymal interstitial lung diseases such as surfactant protein B deficiency." (PMID 33290561, 2021). "In cystic fibrosis, the genetic contribution of the surfactant protein genes, SFTPB, SFTPC, and SFTPD are contained." (PMID 36203529, 2022).
non-small cell lung carcinoma (7 papers, 2017 to 2026). A group of at least three distinct histological types of lung cancer, including non-small cell squamous cell carcinoma, adenocarcinoma, and large cell carcinoma. "The serum Pro-SFTPB level of patients with non-small cell lung cancer was significantly higher than that of patients with small cell lung cancer." (PMID 37476198, 2023). "Meanwhile, there are some reports approving that surfactant genes such as pro–surfactant protein B (pro-SFTPB) was a promising blood biomarker for non-small-cell lung cancer." (PMID 29152081, 2017). "Recently, the association of recessive homozygotes harboring the CC genotype and heterozygotes with the CT genotype has been demonstrated with reduced plasma pro-SFTPB in non-small cell lung cancer patients, which could also indicate some functional effects of this SNP on gene expression." (PMID 35692980, 2022). "While there was no report about the prognostic function of BMP5, Pro–surfactant protein B (pro-SFTPB) was reported as a promising blood biomarker for non-small-cell lung cancer." (PMID 29152081, 2017).
asthma (5 papers, 2007 to 2026). "It has been reported that chitosan‐based deliver therapeutic surfactant protein B (SP‐B) mRNA can replace SP‐B deficiency and experimental asthma in mouse models and prolonged life in treated mice." (PMID 37206219, 2023). "Lung expression of surfactant protein genes SFTPA (P = 0.048) and SFTPB (P < 0.001), but not SFTPC (P = 0.177) or SFTPD (P = 0.285), was higher in lambs from asthma+beta than those from asthma ewes." (PMID 39436639, 2024).
diabetes (5 papers, 2016 to 2024). "High concentrations of surfactant protein B (HDL) significantly associated with all-cause mortality in hemodialysis patients with type 2 diabetes mellitus." (PMID 35300983, 2022). "Previous studies have linked elevated levels of SFTPB in HDL with heart disease, diabetes, and renal disease." (PMID 35300983, 2022).
pneumonia (5 papers, 2008 to 2022). An acute, acute and chronic, or chronic inflammation focally or diffusely affecting the lung parenchyma, caused by an infection in one or both of the lungs (by bacteria, viruses, fungi, or mycoplasma.). "Among nearly 400 children with pneumonia, of whom the most severely affected had PARDS and need for mechanical ventilation, an association was demonstrated between SFTPB Single nucleotide polymorphisms (SNPs) and need for mechanical ventilation." (PMID 35913450, 2022).
chronic lung disease (4 papers, 2005 to 2021). According to the definitions of the American and British Thoracic Societies, including pulmonary functional tests, X-rays, and CT scans for items such as fibrosis, bronchiectasis, bullae, emphysema, nodular or lymphomatous abnormalities. "Similarly, pro-SP-B forms of variable sizes have been detected in lung homogenates from some children with chronic lung disease but were predominantly absent in patients with SFTPB mutations." (PMID 16042774, 2005).
fibrosis (4 papers, 2016 to 2025). the formation of excess fibrous connective tissue in an organ or tissue in a reparative or reactive process. "Pro-SFTPB levels in serum EVs are positively associated with those in lung tissues during progressive fibrosis in a mouse model." (PMID 38855869, 2024). "Here, pro-SFTPB protein levels were transiently increased during the development of bleomycin-induced fibrosis, commonly in lung tissue and serum EVs, suggesting that the dynamics of pro-SFTPB in serum EVs reflect those in fibrotic lung tissues." (PMID 38855869, 2024). "Certain mutations, particularly in SFTPB, are associated with lethal neonatal respiratory distress, whereas others, such as SFTPC mutations, may present later in childhood with a broader range of phenotypes, including interstitial pneumonitis, fibrosis, or restrictive lung disease." (PMID 41303225, 2025).
pulmonary alveolar proteinosis (4 papers, 2005 to 2020). A rare lung disorder characterized by the filling of the pulmonary alveoli with proteinaceous material which stains positive with periodic acid-Schiff stain. "Pre-clinical studies investigated gene correction in hereditary pulmonary alveolar proteinosis with CSF2RA mutations and in surfactant protein B deficiency, while stem cells have been used to correct pulmonary alveolar proteinosis in CSF2RB deficient mice models." (PMID 33316882, 2020).
squamous cell carcinoma (4 papers, 2002 to 2021). A carcinoma arising from squamous epithelial cells. "The level of Pro-SFTPB, CA125, and Cyfra21-1 were higher in patients with squamous cell carcinoma (SCC) than those with adenocarcinoma (ADC) and small cell cancers (SCLC)." (PMID 33854584, 2021).
alveolar proteinosis (3 papers, 2005 to 2025). "SP disorders may result in alveolar proteinosis and include surfactant protein B deficiency (SP-B), surfactant protein C deficiency (SP-C), and mutation in the genes encoding adenosine triphosphate binding cassette protein member A3 (ABCA3) and thyroid transcription factor (NKX2.1)." (PMID 40678364, 2025).
injury (3 papers, 2013 to 2023). Damage inflicted on the body as the direct or indirect result of an external force, with or without disruption of structural continuity. "With smoking or acute lung injury, lung BAL protein concentrations of SFTPB decrease." (PMID 24386300, 2013).
breast carcinoma (2 papers, 2024 to 2025). "Compared with tumors at the primary site, breast cancer tumors that metastasize to the lung show greater expression of genes that are more closely related to lung-specific functions, such as SFTPB and SFTA2." (PMID 40500539, 2025).
lung squamous cell carcinoma (2 papers, 2002 to 2022). "Exosomal TP63, KRT5, CEACAM6, and SFTPB mRNAs can be used as biomarkers to differentiate between lung squamous cell carcinoma (LUSC) and lung squamous cell carcinoma (LUAD), thereby, providing a novel strategy for their differential diagnosis and treatment." (PMID 35584089, 2022).
respiratory infection (2 papers, 2023 to 2024). "However, interactions with other variants (for example, variants of SFTPB or SFTPC) or with external, environmental factors (for example, respiratory infections or smoking) may induce changes in the phenotype." (PMID 39457702, 2024).
Respiratory insufficiency (2 papers, 2018 to 2019). "Surfactant Protein B (SP-B) deficiency is a congenital lung disorder characterized by severe respiratory insufficiency and is unresponsive to any treatment except lung transplantation." (PMID 30781363, 2019).
small cell lung carcinoma (2 papers, 2002 to 2023). Small cell lung cancer (SCLC) is a highly aggressive malignant neoplasm, accounting for 10-15% of lung cancer cases, characterized byrapid growth, and early metastasis. "Because SP-B is essential for spreading of surfactant, we analysed a large gene variation within intron 4 of the surfactant protein B gene in a case–control study in patients with small cell lung cancer (SCLC) and non small lung cancer (NSCLC), their matched control and healthy individuals." (PMID 12107845, 2002).
atherosclerosis (1 paper, 2022). A disease characterized by the build-up of fatty material and calcium deposition in the arterial wall resulting in partial or complete occlusion of the arterial lumen. "Although previous studies have shown that high plasma levels of SFTPB associate with prevalent atherosclerosis only in smokers, we found that SFTPB predicted incident CVD in T1DM independently of smoking status and a wide range of confounding factors, including HDL-C, LDL-C, and triglyceride levels." (PMID 35300983, 2022). "Our observations suggest that SFTPB is unlikely to promote atherosclerosis and CVD risk in T1DM subjects by impairing CEC or the anti-inflammatory effects of HDL on endothelial cells." (PMID 35300983, 2022). "Our observations strongly suggest that the association of SFTPB in HDL with incident CVD and atherosclerosis in T1DM subjects is independent of smoking status." (PMID 35300983, 2022).
edema (1 paper, 2022). An abnormal accumulation of fluid beneath the skin, or in one or more cavities of the body. "Hypothetically, pulmonary edema—as a part of generalized edema—might be the cause; another possibility is surfactant dysfunction due to hypoglycosylation of surfactant protein B and surfactant protein A, but these considerations are beyond the subject of this paper." (PMID 36583024, 2022).
gastric adenocarcinoma (1 paper, 2024). "We have previously reported that gastric adenocarcinoma of the fundic gland type shows high expression levels of SFTPB and SFTPC, both of which are transactivated by the ectopic expression of NKX2-1/TTF1." (PMID 37962678, 2024).
Granuloma (1 paper, 2024). A compact, organized collection of mature mononuclear phagocytes, which may be but is not necessarily accompanied by accessory features such as necrosis. "It is known that SFTPC and SFTPB are characteristic genes of alveolar epithelium, representing the normal lung tissue component involved in the heterogeneity of tuberculosis granulomas." (PMID 39431015, 2024).
Hypertension (1 paper, 2023). The presence of chronic increased pressure in the systemic arterial system. "ISLR2 was found to be associated with hypertension, and SFTPB displayed an association with Granulysin." (PMID 37735436, 2023).
infant respiratory distress syndrome (1 paper, 2020). "Preterm born pigs in a spontaneous nontreated infant respiratory distress syndrome (IRDS) study showed consolidated lungs, immature alveolar architecture and minimal surfactant protein-B expression (SP-B) at GDA 98 and GDA 100 (term at 114 days)." (PMID 33396805, 2020).
lymphoma (1 paper, 2024). A malignant (clonal) proliferation of B- lymphocytes or T- lymphocytes which involves the lymph nodes, bone marrow and/or extranodal sites. "To identify specific predictive biomarkers, we selected five biomarkers (F5, FLT4, GNPTG, IL-17A, and SFTPB) that were differentially expressed between the R and NR patient groups in both lymphoma cohorts from the top 20% of significantly differentially expressed proteins (p < 0.05)." (PMID 38349411, 2024). "To address this question, we validated eight plasma proteins (IL-17A, F5, FLT4, SFTPB, and GNPTG in lymphoma, TNFSF12, CCL3, and KIT in NSCLC) for response prediction and three plasma proteins (IL36G, SERPINC1, and LTA) for relapse monitoring." (PMID 38349411, 2024). "Five noninvasive biomarkers (FLT4, SFTPB, GNPTG, F5, and IL-17A) were further validated in an independent lymphoma cohort (n = 39), and another three noninvasive biomarkers (KIT, CCL3, and TNFSF1) were validated in NSCLC cohort (n = 76)." (PMID 38349411, 2024).
pulmonary surfactant metabolism dysfunction type 1 (1 paper, 2022). "Pathogenic recessive mutations in SFTPB are associated with SP-B deficiency, known as pulmonary surfactant metabolism dysfunction type 1 (OMIM #265120)." (PMID 35692980, 2022).
uremia (1 paper, 2015). A clinical syndrome associated with the retention of renal waste products or uremic toxins in the blood. "They determined that uremic HDL was enriched with surfactant protein B (SP-B), ApoC2, SAA, and α-1-microglobulin/bikunin precursor (AMBP) and demonstrated that SAA in uremia-HDL can promote inflammatory cytokine production." (PMID 26090384, 2015).
cancer (22 papers, 2002 to 2026). A tumor composed of atypical neoplastic, often pleomorphic cells that invade other tissues. "Through correlation analysis, we observed that LAD1 expression levels were statistically associated with several cancer-related genes, including SFTPB, S100A6, CEACAM6, KRT19, S100A10, ANXA2, S100A11, and CAPN2." (PMID 41423496, 2025). "Here, we used clinical sample analysis and a series of experiments to clearly indicate that low expression of pro-SFTPB causes Akt pathway activation and cancer recurrence in patients with early-stage NSCLC." (PMID 37946295, 2023). "In conclusion, the downregulation of pro-SFTPB in rNSCLC is an important factor in activating eIF4F-mediated cancer stemness and immune evasion to induce resistance to immunotherapy and promote disease progression." (PMID 42157944, 2026). "In vitro and animal experiments have shown that pro-SFTPB inhibits cancer stemness and immune evasion in NSCLC, and promotes the efficacy of PD-1 inhibitors." (PMID 42157944, 2026). "Using the EBUS specimen, targeted sequencing was performed and revealed that the cancer harbored noncoding indels in the SFTPB gene, leading to a diagnosis of mediastinal lung cancer." (PMID 30999697, 2019). "Mechanistically, eIF4F promotes pro-SFTPB expression, while pro-SFTPB inhibits the formation of eIF4F complex by binding to eIF4A1, thereby suppressing the translation c-myc and PD-L1 that promote cancer stemness and immune evasion." (PMID 42157944, 2026). "Fifteen of the proteins we identify associated with cancer risk, including SFTPB and GAS1, did not appear to be under active current investigation as a drug target." (PMID 38684708, 2024). "In the present study, we evaluated the possibility that low expression of pro-SFTPB in cancer tissue compared to adjacent tissue is a predictor of early-stage NSCLC recurrence and elucidated the mechanism by which downregulation of pro-SFTPB expression promotes early-stage NSCLC recurrence." (PMID 37946295, 2023). "When the original risk score was analyzed as a continuous outcome in the benign (low and high) subgroup as well as the “low and cancer” subgroup, the common proteins between the two subgroups, SFTPB and CEACAM5, were added to AKR1B10 to explain the variation of the risk scores." (PMID 37760474, 2023). "Similar to the overall transcriptional profile of cancer cells in the GG component samples, surfactant-associated proteins (SFTPA1, SFTPA2, SFTPB, SFTPC, and SFTPD) were highly expressed, and the expression level was higher than that of other cancer cell subclusters of the GG component samples." (PMID 35874770, 2022). "Furthermore, cancer cells in GGN highly expressed alveolar type II (AT2) cell-related marker genes (SFTPA1, SFTPA2, SFTPB, ABCaC3), suggesting that cancer cells in GGN might originate from AT2 cells." (PMID 37745301, 2023). "GGN cancer cells express significantly higher levels of surfactant-related proteins than SN cancer cells, such as surfactant protein (SFTP) A1, SFTPA2, and SFTPB." (PMID 37745301, 2023). "The seven subclusters included alveolar cells, pathological alveolar cells expressing both normal respiratory cell markers (SFTPB, AGR3) and genes related to cancer progression (SPINK1, MET), as well as five cancer subsets." (PMID 36973297, 2023). "Cancer cells were identified with canonical markers of LUAD and alveolar epithelial cells (e.g., SFTPB, SFTPC, EPCAM, NAPSA, and NKX2-1)." (PMID 35874770, 2022). "In comparison to ciliated, Club/Clara cells, pulmonary alveolar type 1 (AT1) and pulmonary alveolar type 2 (AT2), the EGFRex19 cancer cell cluster was characterized by high expression of NPC2 and surfactant genes SFTPB, SFTPC, and SFTPD." (PMID 33712615, 2021). "Targeted sequencing was performed using a surgical specimen and it showed that the cancer harbored noncoding indels in the SFTPA1 and SFTPB genes." (PMID 30999697, 2019).